EEF2K (eukaryotic elongation factor 2 kinase)
Diseases named in the same sentence as EEF2K in open-access papers (continued):
Sharing a sentence is not in itself a finding about the gene and the disease.
triple-negative breast carcinoma (19 papers, 2014 to 2026). An invasive breast carcinoma which is negative for expression of estrogen receptor (ER), progesterone receptor (PR), and human epidermal growth factor receptor 2 (HER2). "Eukaryotic elongation factor 2 kinase (eEF2K) has been considered as a putative target for cancer therapy; however, the underlying mechanisms of eEF2K in triple-negative breast cancer (TNBC) progression remain to be fully elucidated." (PMID 39950798, 2025). "Downregulation of miRNA-22 in triple-negative breast cancer (TNBC) is associated with upregulation of eukaryotic elongation 2 factor kinase (eEF2K) protein, which regulates tumor growth, chemoresistance, and tumor immunosurveillance." (PMID 35294699, 2022). "TQ decreased the expression of Eukaryotic elongation factor-2 kinase (eEF-2K), which was associated with decreased proliferation, migration, invasion, and colony formation of triple-negative breast cancer cells both in vitro and in vivo." (PMID 32952942, 2020). "Eukaryotic elongation factor 2 kinase (eEF2K, eEF2-Kinase) is an oncogenic kinase overexpressed in various aggressive solid tumors, including triple-negative breast cancer, pancreatic, ovarian, and lung cancer." (PMID 40725039, 2025). "We and others have previously shown that eEF2K drives cell proliferation, migration, invasion, and tumor growth in triple-negative breast cancer, ovarian cancer, lung cancer, and pancreatic cancers." (PMID 40725039, 2025). "eEF2K has been found to be related with various malignancies, including triple-negative breast cancer, glioma, pancreatic cancer, lung cancer and neuroblastoma." (PMID 39592671, 2024). "The study by Wang and colleagues (2019) investigated the role of autophagy and its regulator, eukaryotic elongation factor 2 kinase (eEF2K), in determining the biological nature of triple-negative breast cancers (TNBCs)." (PMID 39061201, 2024). "For instance, microRNA 603 inhibits tumor formation in triple-negative breast cancer by the targeted inhibition of eEF2K." (PMID 33673713, 2021). "Another study also showed that the eukaryotic elongation factor-2 kinase (eEF-2K) was highly expressed in triple-negative breast cancer cells, promoting cell proliferation, migration, and invasion." (PMID 32655665, 2020). "Eukaryotic elongation factor 2 kinase (eEF2K), a stress-responsive regulator of translational elongation, has emerged as a pivotal therapeutic target in triple-negative breast cancer (TNBC) due to its critical role in sustaining cancer cell survival under nutrient stress." (PMID 41589674, 2026). "They reported significant in vivo tumor integration of miR-329 and inhibition of the eukaryotic elongation factor-2 kinase (eEF2K) protein in multiple triple-negative breast cancer (TNBC) models with pronounced anti-tumor efficacy and without any side effects in mice." (PMID 38370484, 2024). "The eukaryotic elongation factor-2 kinase, eEF2K, which restricts protein translation elongation, has been identified as a potential therapeutic target for diverse types of malignancies including triple negative breast cancer (TNBC)." (PMID 33911160, 2021). "In another study, in vivo administration of thymoquinone (20 and 100 mg/kg) significantly decreased the progression of MDA-MB-231 tumors and inhibited the eukaryotic elongation factor 2 kinase (eEF-2K) in an orthotopic tumor mouse model of triple-negative breast cancer." (PMID 32823812, 2020). "Previously, our group showed the binding interaction between eEF2K and FOXM1 in triple negative breast cancer." (PMID 40725039, 2025). "In this study, we examined the role of Forkhead Box M1 (FOXM1) proto-oncogenic transcription factor in triple negative breast cancer (TNBC) cells and the regulation of eEF2K." (PMID 26918606, 2016).
lung carcinoma (14 papers, 2016 to 2025). "Some recent reports suggest that eEF2K forms a complex with STAT3 in lung cancer cells, and the loss of eEF2K can result in decreased expression of STAT3." (PMID 37875468, 2023). "For example, Vitamin K2, which ranks in the top 10 purchasable candidates, has a high possibility to be a new eEF2K inhibitor because it has been reported to induce lung carcinoma cell apoptosis." (PMID 35956836, 2022). "eEF2K inhibits the aerobic glycolysis of lung cancer cells by the blockage of pyruvate kinase M2 isoform (PKM2) dimerization and inactivation of STAT3, leading to the impairment of tumor growth." (PMID 34532346, 2021). "Another experiment on human lung cancer cells showed that eEF2K protects cell survival under nutrient deprivation, but this effect is due to its inhibition of protein synthesis rather than regulation of autophagy." (PMID 33673713, 2021). "It was found that overexpression of eEF2K permits increased tumor-cell survival in many types of cancer, including breast, brain, pancreatic, and lung cancer." (PMID 34532346, 2021). "In this study, we unexpectedly found that eEF2K acts as cancer suppressor distinct from its role of cytoprotection in lung cancer cells." (PMID 32054489, 2020). "We further examined cell growth using plate colony formation assays and found that eEF2K depletion promoted cell growth, further supporting that eEF2K inhibits lung cancer cell proliferation." (PMID 32054489, 2020). "We showed here that eEF2K functioned as cancer suppressor in lung cancer cells, which inhibited tumorigenesis by blocking cell proliferation independent of its role in protein synthesis." (PMID 32054489, 2020). "A recent study found that Eukaryotic Elongation Factor-2 kinase (eEF-2K) expression was related to shorter overall survival in lung cancer patient." (PMID 32742772, 2020). "Thereby, eEF2K inhibits the aerobic glycolysis of lung cancer cells and then impairs cells proliferation and tumor growth." (PMID 32054489, 2020). "We demonstrated that eEF2K inhibited lung cancer cells proliferation and affected the inhibitory effects of EGFR inhibitor gefitinib." (PMID 32054489, 2020). "A line of A549 lung carcinoma cells harbouring an IPTG-inducible shRNA against the EEF2K mRNA was developed." (PMID 26795954, 2016). "Similarly, it was found after knocking out eEF2K that the invasion and metastasis of lung cancer cells was inhibited." (PMID 33673713, 2021). "Similarly, eEF2K is positively correlated with lung cancer proliferation, invasion and metastasis, and poor prognosis." (PMID 33673713, 2021). "In contrast, a study using human lung carcinoma (A549) cells and embryonic fibroblasts from eEF2K knockout or control mice failed to confirm a role for eEF2K in regulating autophagy, although eEF2K did display the expected cytoprotective effect in the face of nutrient deprivation." (PMID 29186827, 2017). "Together with the previous study showing that eEF2K enhances PD-L1 expression in prostate and lung cancer cells via promoting PD-L1 mRNA translation and protein synthesis, the regulatory effects of eEF2K on PD-L1 may result from translational as well as post-translational modifications." (PMID 35347072, 2022). "As for prostate and lung cancer cells, a study from Wu has shown that the absence of eEF2K has reduced the expression of PD-L1 protein, an immune checkpoint protein, to help cancer cells to escape from immune cells." (PMID 34532346, 2021).
glioma (13 papers, 2012 to 2025). A benign or malignant brain and spinal cord tumor that arises from glial cells (astrocytes, oligodendrocytes, ependymal cells). "It was also found that silencing of eEF2K can inhibit autophagy through the mTORC1/p70S6K signaling pathway and increase the sensitivity of human glioma cells to 2-deoxy-d-glucose (2-DG)." (PMID 33673713, 2021). "Previous studies, many of them in glioma cells, have indicated that eEF2K is a positive regulator of autophagy, a process which can aid the survival of nutrient-starved cells." (PMID 26795954, 2016). "It was reported that 30 significantly inhibits eEF2K at concentrations that are relevant both in vitro and in vivo, and this could explain its antiproliferative activity on human glioma cells and blockage of gliomal cells at the G1–S interface." (PMID 33673713, 2021). "Thus Bcl-xl plays an important role in inhibiting TRAIL-induced apoptosis in this setting, while eEF2K coordinates TRAIL-modulated Bcl-xL expression in glioma cells." (PMID 29186827, 2017). "In view of earlier findings, largely from glioma cells, we considered it important to assess whether eEF2K played a role in regulating autophagy in other cell types and situations." (PMID 26795954, 2016). "Several studies have suggested that eEF2K may regulate (promote) autophagy in glioma cells or mouse embryonic fibroblasts, such that it might provide a link between mTORC1 signalling and the regulation of autophagy." (PMID 26795954, 2016). "Compound NH125 was able to inhibit eEF2K kinase activity remarkably, with in vitro IC50 of 60 nM, in addition to glioma cell line experiments where NH125 treatment provided 10-fold resistance when eEF2K was overexpressed." (PMID 36770760, 2023). "Inhibiting eEF2K-mediated autophagy has been reported to enhance the antitumor effect of MK-2206, an AKT inhibitor, on human nasopharyngeal carcinoma and human glioma cells." (PMID 33673713, 2021). "Disabling eEF2K, either by siRNA or using NH125, was found to sensitise glioma cells to the pro-apoptotic stimulus TRAIL." (PMID 29186827, 2017). "In glioma (TG098 or LN229) cells, silencing of eEF2K augmented the pro-death effects of the PKB inhibitor MK-2206." (PMID 29186827, 2017). "Eukaryotic elongation factor-2 kinase (eEF-2 kinase, also known as calmodulin-dependent protein kinase III), a critical enzyme controlling protein translation, is up-regulated in several types of malignancies, including gliomas." (PMID 26830677, 2016). "We have been investigating the roles and implications of eukaryotic elongation factor-2 kinase (eEF-2 kinase, also known as Ca2+/calmodulin-dependent protein kinase III), a critical enzyme that controls protein translation and is up-regulated in glioma and several other types of human cancer." (PMID 24303044, 2013).
colon cancer (11 papers, 2015 to 2024). "Given that protein synthesis is the most ATP consuming process in the cell, failure to block mRNA translation elongation is expected to lead to ATP depletion in eEF2K deficient cells exposed to cisplatin, as shown in colon cancer cells under basal conditions." (PMID 39003251, 2024). "The expression of eEF2K is downregulated in colon cancer patients, which is associated with worse overall survival." (PMID 34532346, 2021). "On the contrary, overexpression of eEF2K reduced the viability of colon cancer cells and enhanced the antitumor effect of the chemotherapy drug Oxaliplatin20." (PMID 39592671, 2024). "The negative regulation of eEF2K on autophagy in colon cancer cells is dependent on the activation of the AMPK-ULK1 pathway." (PMID 33673713, 2021). "In contrast, overexpressing EEF2K reduced colon cancer cell viability and potentiated the anti-tumor efficacy of the chemotherapeutic drug oxaliplatin." (PMID 31266475, 2019). "Consistently, De Gassart and co-workers reported that nelfinavir exerted its anti-tumor effect in colon cancer cells in an EEF2K-dependent manner." (PMID 31266475, 2019). "eEF2K is overexpressed in solid cancers, including pancreatic and colon cancer and glioblastoma, and correlates with poor patient survival." (PMID 26918606, 2016). "Indeed, there have been reports indicating that silencing eEF2K expression results in reduced production of ROS in vascular smooth muscle cells and human colon cancer cells." (PMID 37875468, 2023). "However, contradictory studies have surfaced at which point eEF2K disrupts the growth of certain cancers, including colon tumors, intestinal tumors, and lung tumors." (PMID 34532346, 2021). "In addition, silencing of eEF2K has been reported to promote autophagic survival via indirect activation of the AMPK-ULK1 pathway in colon cancer cells." (PMID 30547775, 2018). "eEF2K is an emerging therapeutic target in TNBC and other aggressive cancers including pancreatic, and colon cancers and glioblastoma, and its overexpression correlates with poor patient survival." (PMID 26918606, 2016). "A further study, using colon cancer cells, indicated that, rather than activating autophagy, knockdown of eEF2K actually promoted autophagy." (PMID 29186827, 2017).
Alzheimer disease (8 papers, 2016 to 2026). A progressive, neurodegenerative disease characterized by loss of function and death of nerve cells in several areas of the brain leading to loss of cognitive function such as memory and language. "Consistently, recent studies show that the inhibition of the eEF2K signaling via genetic or pharmacological approaches can alleviate synaptic failure and dementia syndromes in mouse models of Alzheimer's disease (AD) and related dementias (ADRDs)." (PMID 41896174, 2026). "High levels of phosphorylated eEF2 have been described in Alzheimer disease, Parkinson disease and genetic epilepsy and it has also been reported that inhibition of eEF2K activity ameliorate the pathology." (PMID 34980259, 2022). "Therefore, investigating eEF2K proves beneficial in uncovering the pathogenesis of prominent neurodegenerative diseases, including Alzheimer’s disease and Parkinson’s disease." (PMID 39180059, 2024). "Notably, we also reported that eEF2K (mRNA) expression and/or activity is pathologically increased in post-mortem PD and Alzheimer disease brains, as well as in relevant transgenic rodent models including the moribund M83+/+ mice." (PMID 34092244, 2021). "In addition, high levels of p-eEF2 were also reported in a mouse model of Alzheimer’s disease and in brain material of patients affected by Alzheimer’s disease, suggesting a particular role of the eEF2K/eEF2 pathway in mental disorders." (PMID 27826228, 2016). "High levels of P-eEF2 were reported in a mouse model of Alzheimer’s disease and in brain samples of patients affected by Alzheimer’s disease as a consequence of the pathological activation of AMPK followed by the activation of eEF2K." (PMID 34980259, 2022).
colorectal cancer (8 papers, 2016 to 2024). A primary or metastatic malignant neoplasm that affects the colon or rectum. "Genetic inactivation of Eef2k reverses the reduced tumorigenesis following Rpl24Bst mutation in Apc-deficient Kras-mutant models of colorectal cancer (CRC)." (PMID 34895463, 2021). "Finally, RPL24, which we found elevated across our analyses, is known to enhance translation and promote tumorigenesis; its functional inactivation through mutation suppressed colorectal cancer by promoting eEF2 phosphorylation via eEF2K." (PMID 37888706, 2023). "The low expression of eEF2K in COAD suggests that enhanced eEF2K activity is beneficial for colorectal cancer patients, which is consistent with previous findings." (PMID 39592671, 2024). "We made use of one such inhibitor (JAN-849) to explore the role of eEF2K in the ability of colorectal cancer (HCT116) cells to withstand deprivation for glucose, an important fuel for generating energy." (PMID 26795954, 2016). "Thus, low eEF2K activity is required for rapid proliferation, which is consistent with low eEF2K correlating with poor survival in colorectal cancer patients." (PMID 32298235, 2020). "However, an opposite role of EEF2K in colorectal cancer has been reported, in which EEF2K could be directly inhibiting key protein synthesis or indirectly suppressing the activation of autophagy via accumulated cellular ATP levels." (PMID 35184394, 2022). "Expression of RPL24, EEF2K, and EEF2 is consistent with increased eEF2 activity in colorectal cancer (CRC) tumours." (PMID 34895463, 2021). "EEF2K has tumor-suppressing effects upon colorectal cancer, in which silencing of eEF2K induces survival-promoting autophagic responses through the AMPK-ULK pathway and promotes the growth of colorectal cancer by increasing cell size, survival rate, and clonogenicity." (PMID 39592671, 2024). "In addition, there are data to suggest that the benefits of low eEF2K activity in cancer may not be limited to colorectal cancer." (PMID 32298235, 2020).